EGFR (epidermal growth factor receptor)
Diseases named in the same sentence as EGFR in open-access papers (continued):
Sharing a sentence is not in itself a finding about the gene and the disease.
adenoid cystic carcinoma (17 papers, 2007 to 2025). A malignant tumor arising from the epithelial cells. "EGFR was mutated in one patient with adenoid cystic carcinoma." (PMID 35267442, 2022). "The average EGFR immunohistochemical score was 3 ± 0 for the adenoid cystic carcinoma subgroup and 2.67 ± 0.47 for acinic cell carcinoma." (PMID 40095737, 2025). "The results were in line with previous findings that EGCG inhibited the growth of salivary adenoid cystic carcinoma cells via the EGFR/Erk signal-transduction pathway and the mitochondria pathway." (PMID 33747527, 2021). "Antagonists of EGFR can suppress the growth of several malignancies; however, their therapeutic effect in adenoid cystic carcinoma (ACC) is controversial." (PMID 23496982, 2013). "Overexpression of transmembrane receptors of type tyrosine kinase have been reported (HER2/neu, EGFR, C-kit in adenoid cystic carcinoma)." (PMID 24386625, 2013). "EGFR is present in salivary gland tumors, with expression reported in 0% to 85% of adenoid cystic cancers." (PMID 23231994, 2012). "In this study, we have investigated the effects of a combination of tyrosine kinase inhibition of EGFR and uPAR down-regulation on EGFR signaling pathway in adenoid Cystic Carcinoma (ACC) cell lines." (PMID 18519000, 2008). "Hence another questions remains: patients with adenoid cystic carcinoma may also benefit from combined treatment with i.e. new substances such as EGFR-inhibitors in terms of local and distant control." (PMID 22551422, 2012). "In the present study, we evaluated the relationship between c-kit, EGFR, and VEGF expression and the survival or local control rate of adenoid cystic carcinoma." (PMID 23231994, 2012). "In this study, the expression of c-kit, EGFR, and VEGF in adenoid cystic cancer was evaluated, and the relationships between the expression of these markers and the clinical findings were investigated." (PMID 23231994, 2012). "The low response rate of adenoid cystic cancer to tyrosine kinase inhibitors and EGFR inhibitors indicates that no single molecule is dominant in tumor invasion and spread of this cancer." (PMID 23231994, 2012). "EGFR overexpression and the absence of c-kit expression are negative prognostic factors in adenoid cystic cancer." (PMID 23231994, 2012). "The other question is whether patients with adenoid cystic carcinoma will profit from combined treatment with i.e. new substances such as EGFR-inhibitors, which will potentially not increase treatment-related side effects significantly in terms of local and distant control." (PMID 22046954, 2011). "Despite the high expression levels of c-kit, EGFR, and VEGF, these markers were not significantly correlated with recurrence and the prognosis of adenoid cystic cancer." (PMID 23231994, 2012). "All 4 adenoid cystic carcinomas cluster together in branch III and 5/7 of the apocrine tumors cluster together in branch V. All 18 tumors in branch II are positive for KRT5/6 staining, 97% of the tumors in branch I are EGFR negative, and all 14 tumors in branch V are KIT negative." (PMID 17910759, 2007).
alopecia (17 papers, 2009 to 2026). Hair loss usually from the scalp. "Whether EGFR deficiency is an inciting event in human alopecia, or merely a secondary (perhaps inflammation-driven) event that further sensitizes keratinocytes to interferon signaling, is not yet resolved by the available data." (PMID 39521936, 2024). "Thus, loss of EGFR suppressed cyclophosphamide-induced apoptosis and caused resistance to alopecia, suggesting EGFR plays a pro-apoptotic role in chemotherapy-induced alopecia." (PMID 23894460, 2013). "To determine whether EGFR deficiency attenuated cyclophosphamide-induced alopecia by altering cell cycle, we examined proliferation following cyclophosphamide treatment." (PMID 23894460, 2013). "In order to determine whether these data are relevant clinically, secondary analysis of clinical trials utilizing EGFR-targeting agents together with chemotherapeutics that cause alopecia was undertaken, revealing evidence of a role for EGFR in alopecia in cancer patients." (PMID 23894460, 2013). "Studies assessed capecitabine-induced hand-foot syndrome (HFS), multikinase inhibitor-induced hand-foot skin reaction (HFSR), taxane-induced alopecia, and epidermal growth factor receptor (EGFR) inhibitor-related skin toxicities." (PMID 41989665, 2026). "For example, epidermal growth factor receptor (EGFR) and CDK4/6 inhibitors are linked to acneiform eruptions and alopecia; capecitabine is associated with hand-foot syndrome; and ICIs with immune-mediated mucocutaneous reactions." (PMID 40868155, 2025). "On the other hand, alopecia as a side effect of EGFR inhibitors has been documented by many studies." (PMID 38454571, 2024). "When patients are treated with EGFR-TKIs, 0–13% patients manifest hair abnormalities, including alopecia, eyelash changes and excessive hypertrichosis." (PMID 32179761, 2020). "Both skin-targeted Egfr mutant mice and EGFR inhibitor-treated mice were resistant to cyclophosphamide-induced alopecia." (PMID 23894460, 2013). "A trend of reduced alopecia with EGFR targeting appeared in the trials utilizing small molecule inhibitors of EGFR." (PMID 23894460, 2013). "Taken together, our results demonstrated the involvement of EGFR signaling in chemotherapy-induced alopecia, which will help in the design of novel therapeutic regimens to minimize chemotherapy-induced alopecia." (PMID 23894460, 2013). "In contrast, EGFR inhibitor treated and cyclophosphamide injected mice sustained substantially less alopecia (middle and right-hand panels)." (PMID 23894460, 2013). "Treatment of control mice with the EGFR inhibitors erlotinib or gefitinib similarly suppressed alopecia and catagen progression by cyclophosphamide." (PMID 23894460, 2013). "Our conclusions about the role of EGFR in cyclophosphamide-induced alopecia were initially derived from a model with conditional deletion of the receptor." (PMID 23894460, 2013). "Secondary analysis of clinical trials utilizing EGFR-targeted therapies and alopecia-inducing chemotherapy also revealed evidence for involvement of EGFR in chemotherapy-induced alopecia." (PMID 23894460, 2013). "Since EGFR signaling plays a vital rolein the initiation of hair growth, interruption of EGFR signaling can result indisorganized hair follicles leading to follicular necrosis and alopecia." (PMID 19424511, 2009). "Anti-EGFR molecules present a certain risk of non-scarring alopecia, sometimes completed with a scarring pattern as a consequence of the iatrogenic anti-EGFR facial papulo-pustulosis." (PMID 34771716, 2021). "Thus, EGFR inhibitors administered prior to cyclophosphamide provided partial protection from cyclophosphamide-induced alopecia in mice." (PMID 23894460, 2013). "EGFR-targeted therapy and alopecia rates during chemotherapy." (PMID 23894460, 2013).
alopecia (continued). "In order to determine whether EGFR inhibitors could block cyclophosphamide-induced alopecia, groups of wild type mice were topically treated with EGFR inhibitors erlotinib, gefitinib or vehicle alone prior to cyclophosphamide treatment, and alopecia monitored." (PMID 23894460, 2013). "In contravention to this idea, however, was the suppression of alopecia by EGFR inhibitors." (PMID 23894460, 2013). "We hypothesize that sustained inhibition of EGFR is necessary for reduced alopecia." (PMID 23894460, 2013). "We hypothesized that EGFR signaling is involved in cyclophosphamide-induced catagen and alopecia." (PMID 23894460, 2013). "An EGFR‐MAB therapy may be associated with strong dermatological toxicities, inflammations, Staphylococcus aureus superinfection, and hematopoietic side effects such as papulopustular rush, nail inflammation, dry skin, alopecia, increased growth of eyelashes and facial hair, and strong pruritus." (PMID 37341059, 2023). "TT-induced alopecia (TIA) confirms the necessary activation of several signaling pathways, such as SHH, EGFR and VEGF, in hair physiology." (PMID 34771716, 2021). "The other four trials utilizing cetuximab or panitumumab reported nonsignificantly higher rates of alopecia upon EGFR targeting." (PMID 23894460, 2013). "The two other trials using daily administration of gefitinib or erlotinib had similar, but nonsignificant, trends of decreased alopecia with inhibition of EGFR." (PMID 23894460, 2013). "Because the epidermal growth factor receptor (EGFR) signals anagen hair follicles to enter catagen, we hypothesized that EGFR signaling may be involved in cyclophosphamide-induced alopecia." (PMID 23894460, 2013). "Neutralizing antibodies against EGFR, however, showed no consistent protection from chemotherapy-induced alopecia." (PMID 23894460, 2013). "Nonsignificantly higher rates of alopecia occurred in four EGFR-neutralizing antibody trials." (PMID 23894460, 2013). "During cyclophosphamide-induced alopecia, initial apoptosis resulting from DNA damage may be independent of EGFR, while sustained induction of apoptosis necessary for hair follicle involution is EGFR-dependent." (PMID 23894460, 2013).
anaplastic astrocytoma (17 papers, 2010 to 2024). "The most severe of these likely to have a functional effect was found in the anaplastic astrocytoma case, which saw both a driver mutation (rs149840192, p.A289V) and an amplification of at least five extra copies of the EGFR." (PMID 32570879, 2020). "Amplification and/or overexpression of EGFR have been observed in approximately 50% of malignant gliomas compared to approximately 10 to 26% of anaplastic astrocytomas." (PMID 27437777, 2016). "LOH at 10q is associated with poor survival outcomes for both anaplastic astrocytomas and GBM and the lost or inactive state of PTEN has been linked to the resistance of targeted EGFR inhibitors in GBM." (PMID 24716189, 2014). "The Fisher exact test revealed that the frequency of PTEN and EGFR alterations was significantly higher in higher grade tumors (GBM) in comparison to anaplastic astrocytoma (82% vs 25%, p = 0.007 for PTEN and 54.5% vs. 12.5%, p = 0.047 for EGFR)." (PMID 24358143, 2013). "In our series of anaplastic astrocytomas this approach revealed a relatively high frequency of EGFR gene amplification with 29% of the tumors exhibiting this genetic rearrangement." (PMID 20331873, 2010). "The overexpression of EGFR in anaplastic astrocytomas is in line with our earlier report and other studies." (PMID 20331873, 2010). "The aim of this study was to investigate EGFR gene amplification and expression of c-erbB1-4 receptor proteins in human anaplastic astrocytomas." (PMID 20331873, 2010). "Among GBMs, two cases were originally diagnosed as anaplastic astrocytoma according to WHO 2016 classification; however, CGPT revealed that they harbored EGFR amplification and TERT promoter mutation, and they were reclassified as GBM based on WHO 2021 classification." (PMID 35626060, 2022). "Amplification of EGFR has also been found in anaplastic astrocytomas." (PMID 22691727, 2012). "However, there is limited knowledge concerning the occurrence of EGFR gene amplification and the expression of erb-receptors in anaplastic astrocytomas." (PMID 20331873, 2010). "Consistent with prior discussions, it has been stated that EGFR amplification along with mutation of TERT promoter and 7+/10− are alterations very often present in adult patients with IDH-wild-type GBM, and they can contribute to the upgrade of diffuse or anaplastic astrocytoma to wild-type GBM." (PMID 39057054, 2024). "A recent phase I dose-escalation trial of gefitinib, an epidermal growth factor receptor (EGFR) tyrosine kinase inhibitor (TKI), plus FSRT (18 to 36 Gy in 3 fractions) in 15 patients (11 GBM, 4 anaplastic astrocytoma) showed this combination was well tolerated at all dose levels." (PMID 22530121, 2012).
dysplasia (17 papers, 2007 to 2025). A usually neoplastic transformation of the cell, associated with altered architectural tissue patterns. "Objectives: to investigate the immunoexpression of epidermal growth factor receptor (EGFR) in a sample of oral leukoplakias (OL) and to determine the receptor’s association with dysplasia, tobacco consumption, lesion site, and proliferation rate." (PMID 22322523, 2012). "The present study evaluated the immunoexpression of EGFR in a sample of oral leukoplakia and its association with dysplasia, tobacco consumption, lesion site, and proliferation rates." (PMID 22322523, 2012). "TCM prescriptions have been reported to effectively intervene in PLGC (including chronic atrophic gastritis [CAG], GIM, and dysplasia) via the PI3K/Akt/mTOR or EGFR/PI3K/Akt pathways." (PMID 38096029, 2023). "Of the 21 dysplasia samples, CDKN2A loss was found in four samples, MYC amplification in two, and EGFR in one." (PMID 35897137, 2022). "A surprising high‐level EGFR amplification was observed in a dysplasia sample." (PMID 35897137, 2022). "The EGFR/PI3K/AKT pathway is abnormally activated in the PLGC rat model (including CAG, GIM, and dysplasia), and inhibiting this pathway can effectively improve PLGC." (PMID 38096029, 2023). "Immunoexpression of EGFR was observed in healthy controls (n = 11), OSCC (n = 106), and OPMD with dysplasia (n = 56), which showed significant expression with increasing grades of dysplasia and OSCC." (PMID 36010285, 2022). "The current study also attempts to validate the expression of EGFR in tissue samples of OSMF and OSCC using real-time polymerase chain reaction (RT -PCR) and the immunoexpression of EGFR in OPMD with dysplasia and OSCC using IHC." (PMID 36010285, 2022). "Although the Ki-67 LIs value did not correlate with corresponding EGFR positivity or with the presence of dysplasia, the present study confirmed an extended suprabasal expression of Ki-67 in leukoplakia." (PMID 22322523, 2012).
fibrosis (17 papers, 2012 to 2026). the formation of excess fibrous connective tissue in an organ or tissue in a reparative or reactive process. "Small molecule tyrosine kinase inhibitors (TKI) gefitinib and erlotinib, which were used in the mouse fibrosis studies, inhibit the ATP binding pocket of the active conformation of EGFR." (PMID 36490328, 2022). "Pharmacological inhibition of EGFR attenuated receptor phosphorylation and reduced ER stress, cardiac fibrosis, and microvascular dysfunction implying a key role of EGFR in mediating ER stress and subsequent cardiac pathology." (PMID 34408653, 2021). "Moreover, plumbagin may prevent hepatic fibrosis through inhibition of EGFR phosphorylation and STAT3 activation." (PMID 26550019, 2015). "In conclusion, pressure overload enhances the secretion of Wnt5a or Wnt11 from CMs and CFs which promotes cardiac fibrosis by activation the crosstalk of FZD5 and EGFR." (PMID 34564708, 2021). "The matrine derivative MD-1 engages EGFR on HSC-T6 cells to suppress EGFR/AKT phosphorylation, downregulate cyclin D1, and block persistent HSC activation; in DMN–induced rat fibrosis, MD-1 attenuates disease progression, improves liver function, and preserves hepatocyte integrity." (PMID 41293253, 2025). "Some proteins of these genes have already been associated with pathophysiological processes in the kidney: in tubulointerstitial fibrosis (c-MYC, PTEN, STAT3, HIF-1α, PT53); podocyte injury (EGFR, PT53, CTNNB1, CREB1); epithelial-mesenchymal transition (PTEN); and glomerulosclerosis (DICER1, IL1β)." (PMID 37035314, 2023). "Administration of EGFR inhibitors significantly inhibited EGFR phosphorylation, decreased the expression of TGF-β, collagen I and CTGF in the myocardium of animals subjected to HFD, which led to less cardiac fibrosis and dysfunction." (PMID 27087279, 2016).
gliosarcoma (17 papers, 2016 to 2025). A rare histological variant of glioblastoma (WHO grade IV) characterized by a biphasic tissue pattern with alternating areas displaying glial and mesenchymal differentiation (WHO). "It is unclear if the EGFR pathway is indirectly activated in gliosarcoma through other mutations." (PMID 34504233, 2021). "However, gliosarcoma is less frequently associated with EGFR amplification and rarely exhibits IDH mutations." (PMID 29416795, 2018). "Differences in epidermal growth factor receptor (EGFR) mutation type and frequency contrast gliosarcoma from GBM." (PMID 34504233, 2021). "Gliosarcoma mutations with potential therapeutic indications include BRAF, EGFR, CDKN2A, NF1, and PTEN." (PMID 34504233, 2021). "In a comprehensive whole-genome copy number analysis of gliosarcoma, a study found EGFR amplification was uncommon, but found frequent gains of chromosome 7, which contains the EGFR locus, among other genes including CDK6, PDGF-A, and c-Met22." (PMID 34504233, 2021). "Our data supports other studies that show a very low prevalence of EGFR amplification in gliosarcoma, but did show frequent gain of chromosome 7 (72%) containing EGFR locus." (PMID 31073965, 2019). "Our study confirms that EGFR amplification is uncommon in gliosarcoma and provides whole-genome evidence of possible driver pathways from a DNA copy number perspective." (PMID 31073965, 2019). "A Scopus® search for “gliosarcoma and EGFR,” from 1 January 1995 to 31 July 2018 yielded 58 articles, 9 of which included EGFR testing." (PMID 31073965, 2019). "EGFR mutation is less common in gliosarcoma compared to GBM and neither of our patients with gliosarcoma harbored EGFR mutations in their tumors." (PMID 38968484, 2024). "Other genomic analyses of gliosarcoma have found frequencies of EGFR amplification of 4% in a study of 22 samples and 74% EGFR gain in another study of 18 samples with one sample expressing EGFR amplification." (PMID 34504233, 2021). "Therapies targeting EGFR mutations are unlikely to be important treatment options in gliosarcoma due to low frequency of genetic alterations." (PMID 34504233, 2021). "In our study, we found EGFR altered in 12% of gliosarcoma samples." (PMID 34504233, 2021). "Of the detected EGFR amplifications in gliosarcoma, it is speculated that these results are derived from the glial component of the tumor rather than the sarcomatous component." (PMID 31073965, 2019). "Notably, EGFR activation is less frequent in giant cell GB and gliosarcoma." (PMID 41426972, 2025). "Furthermore, the type of EGFR alterations reported in gliosarcoma are not usually seen in GBM; particularly EGFR point mutations have been detected in gliosarcomas (c.1831G > A)." (PMID 31073965, 2019). "Among the most frequently altered genes found in gliosarcoma, BRAF, EGFR, PTEN, NF1, and CDKN2A are potentially targetable according to OncoKB." (PMID 34504233, 2021). "Of the 19 common genes in gliosarcoma, five (BRAF, EGFR, CDKN2A, NF1, and PTEN) were indicated as potentially targetable genes present in the OncoKB database." (PMID 34504233, 2021).